TMPRSS2 (transmembrane serine protease 2)
Diseases named in the same sentence as TMPRSS2 in open-access papers (continued):
Sharing a sentence is not in itself a finding about the gene and the disease.
prostate carcinoma (continued). "Importantly, compared to the most frequently detected TMPRSS2-ERG form (e1e4), e2e4 encodes additional 31 amino acids and accelerated neuroendocrine process of prostate cancer." (PMID 36088396, 2022). "In addition, to involve in the infection of SARS-CoV-2, TMPRSS2 is also closely related to the carcinogenesis of prostate cancer and highly expressed in prostate cancer, and dominated the progression of prostate cancer." (PMID 35558557, 2022). "TMPRSS2 protein expression was highest in prostate cancer followed by urothelial cancer, renal cancer, and pancreatic cancer, and TMPRSS2 was expressed at low levels in lung cancer; TMPRSS2 expression was undetected in the remaining cancer tissue types, including breast cancer." (PMID 36364238, 2022). "The results indicate that TMPRSS2 expression was highest in prostate cancer." (PMID 36364238, 2022). "TMPRSS2-ERG (TE) is a predominant fusion gene with a 55% prevalence in prostate cancer patients." (PMID 35251131, 2022). "Some studies demonstrated that TMPRSS2-ERG could promote prostate cancer metastases and therapy resistance." (PMID 36088396, 2022). "The most strikingly consistent dissimilarities may be the lower frequencies of TMPRSS2-ERG rearrangements, PTEN deletions, and SPOP mutations in prostate cancers from Black men." (PMID 35104804, 2022). "Taken together, it is evident that the TMPRSS2–ERG fusion holds a central role in the onset and progression of prostate cancer, with ERG serving as a pivotal hub for DDR/Hippo/Notch pathways, all actively implicated in prostate cancer pathophysiology." (PMID 35954292, 2022). "As was reported recently in an immunocompromised patient with chronic lymphocytic leukemia (CLL), prostate cancer patients who have very high TMPRSS2 in their cancer may be especially vulnerable and may constantly shed the virus." (PMID 35328625, 2022). "Similarly, treatment with mibolerone induced increase in the TMPRSS2 cleavage product in prostate cancer cells." (PMID 35712238, 2022). "TDRD1 has been discovered to be a direct target of (ETS-related gene) ERG, which promotes tumor initiation and progression in TMPRSS2-ERG fusion prostate cancer and could be a new immunotherapy target." (PMID 36439479, 2022). "Increased TMPRSS2 expression correlated with the poor survival of prostate cancer patients." (PMID 35017320, 2022). "ETS FUSION POSITIVE TUMOURS: E26 Transformation Specific (ETS) transcription factor gene fusions are found in approximately half of prostate cancers, the commonest of which is fusion of the androgen‐responsive promoter Transmembrane Protease Serine 2 (TMPRSS2) with the ERG gene of the ETS family." (PMID 33599076, 2021). "The TMPRSS2-ERG fusion gene arising from genetic rearrangement (fusion of encoding transmembrane protease serine 2, TMPRSS2 gene, and EST-related gene, ERG) has also been a central focus in prostate cancer, which leads to aberrant expression of the ETS transcription factor ERG." (PMID 34630112, 2021). "ADT decreases the levels of TMPRSS2 in prostate cancer patients." (PMID 33391502, 2021). "Moreover, it was previously reported that bromhexine, an FDA-approved ingredient in mucolytic cough suppressants, had the capacity to inhibit TMPRSS2 activity and to reduce prostate cancer enlargement and metastases." (PMID 33578849, 2021). "The TMPRSS2-ERG gene fusion is the most frequent alteration observed in human prostate cancer." (PMID 34230470, 2021). "More than 90% of prostate cancer samples that overexpress ERG harbor the TMPRSS2:ERG fusion gene." (PMID 33634124, 2021). "Compared to TMPRSS2-ERG fusion-negative prostate cancer, fusion-positive prostate cancer harbors distinct risk factors." (PMID 34001144, 2021).
prostate carcinoma (continued). "To further investigate how ERK phosphorylation regulates ERG-mediated transcription we conducted an immunoprecipitation (IP) coupled with mass spectrometry of total cellular ERG from VCaP prostate cancer cells which express ERG due to a TMPRSS2/ERG gene rearrangement." (PMID 34314419, 2021). "Bromhexine, another potent TMPRSS2-specific protease inhibitor, was identified through large-scale chemical library screening and was demonstrated to lower the risk of metastasis in prostate cancer with no systemic toxicity shown." (PMID 34001144, 2021). "Transmembrane protease serine 2:v-ets erythroblastosis virus E26 oncogene homolog (TMPRSS2-ERG) fusion is the single most frequent genetic alteration in prostate cancer; a fusion of Erythroblast Transformation Specific (ETS) family genes with the protease gene TMPRSS2." (PMID 33917592, 2021). "TMPRSS2 codes for a transmembrane serine protease, which can stimulate a proteolytic cascade to promote degradation of extracellular matrix and the cell invasion of prostate cancer." (PMID 34168096, 2021). "Additionally, TMPRSS2-ERG fusions exist in approximately 50% of prostate cancer cases, with TMPRSS2-FEV, -ETV1, -ETV4, and -ETV5 fusions found in other patients." (PMID 34145397, 2021). "Regulation of TMPRSS2 has primarily been explored in prostate cancer." (PMID 33828231, 2021). "Thus, it is important to assess TMPRSS2 expression in normal and cancer tissues, particular in prostate cancer tissues, for help in predicting the cancer patients’ susceptibility to SARS‐CoV‐2 infection and the disease outcome." (PMID 33609069, 2021). "TMPRSS2-ERG fusions are described in 30-50% of new prostate cancer diagnoses." (PMID 34026653, 2021). "This implies that suppression of the TMPRSS2 expression levels in normal cells might help fight not only prostate cancer developments but also the viral infection." (PMID 33609069, 2021). "In ~50% of prostate cancers a chromosomal rearrangement results in the fusion of the androgen-regulated promoter of TMPRSS2 to the open reading frame of ERG and results in aberrant expression of either full-length, or N-terminally truncated ERG protein in prostate epithelium." (PMID 34314419, 2021). "Although the TMPRSS2-ERG gene fusion is the most common alteration in human prostate cancer, its involvement in disease progression remains unclear." (PMID 34230470, 2021). "TMPRSS2-ETS rearrangements were later characterized in prostate cancer metastases and different metastatic sites from the same patients were found to harbor the same molecular sub-type of gene fusion events, indicating clonal expansion of advanced disease from a single primary focus." (PMID 33634124, 2021). "Because of its prevalence and the availability of fusion-positive cell line model, the relevance of TMPRSS2-ERG for prostate cancer cells and the clinical manifestations of the disease has been widely studied and will be discussed in more detail in the following chapters." (PMID 33634124, 2021). "In addition to AR, TMPRSS2‐ERG rearrangements, resulting from fusion of an ERG oncogene and AR‐driven TMPRSS2 promoter, have been detected in more than 50% of prostate cancer patients." (PMID 33448107, 2021). "For example, the TMPRSS2-ERG fusion is a carcinogenic fusion event in prostate cancer." (PMID 34381020, 2021). "TMPRSS2-ERG gene fusions are the most common form of ETS gene family member fusions in prostate cancer and are mutually exclusive with other ETS family member fusions and a number of other somatic molecular alterations in prostate cancer, such as SPOP mutations or SPINK overexpression." (PMID 34191807, 2021). "It is firmly established that suppression of AR transcriptional activity through reduction in circulating androgens or direct antagonism of AR-androgen binding using AR competitive antagonists reduces expression and protein levels of TMPRSS2 within the prostate, as well as within prostate cancers." (PMID 34225789, 2021).
prostate carcinoma (continued). "Finally, it has to be pointed out that TMPRSS2 has been identified in prostate cancer, and that its expression was upregulated by androgens." (PMID 33578849, 2021). "Early-onset prostate cancer is characterized by a high prevalence of TMPRSS2-ERG fusions." (PMID 33441414, 2021). "Another report revealed that the HGF/ETS pathway could be active in the TCGA molecular subgroup of TMPRSS2/ERG fused prostate cancers (50%)." (PMID 34123781, 2021). "Moreover, androgen deprivation therapy (ADT), a commonly-used treatment for prostate cancer patients, has been shown to lower TMPRSS2 expression." (PMID 33179220, 2021). "Several studies have previously discussed the critical role of TMPRSS2 in the context of SARS-Co-V-2 infection, including a recent review by our team wherein we have discussed the association between TMPRSS2, AR, and SARS-Co-V2 in the context of prostate cancer." (PMID 33915795, 2021). "In addition, TMPRSS2–ERG gene fusions are expressed in early-phase prostate cancer and allow for prognostic evaluation of patients with prostate cancer." (PMID 33557176, 2021). "This hypothesis also applies to TMPRSS2, which was first identified in prostate cancer cells, where it is strongly upregulated in response to androgens." (PMID 32936429, 2021). "The most common chromosomal rearrangement in prostate cancer present in approx. 50% of patients results from the fusion of the androgen-regulated gene, transmembrane protease serine 2 gene (TMPRSS2, chr21q22.2), with E-twenty-six (ETS)-related gene (ERG, chr21q22.3)." (PMID 33924671, 2021). "The increased TMPRSS2 expression could then promote TMPRSS2-ERG fusion events, hence predisposing male SARS-CoV-2-infected patients to prostate cancer." (PMID 32974166, 2020). "Prostate Cancer therapies repurposed for COVID-19 patients: Antiandrogens and TMPRSS2." (PMID 32641750, 2020). "For this study, we selected TMPRSS2:ERG fusion as it represents the most common genomic alteration in prostate cancer as well as the next most prevalent genomic alterations in prostate cancer which included deletion of 3p, 5q, 6q, 8p, 10q23, 12p, 13q, 16q, 17p, and 18q." (PMID 33339518, 2020). "Additionally, the fact that signaling through the androgen receptor (AR) axis facilitates prostate cancer development, suggests a relationship between TMPRSS2 and prostate cancer." (PMID 32974166, 2020). "Interestingly, TMPRSS2 has been widely studied in the context of prostate cancer, where it is highly expressed, and TMPRSS2 expression is increased in response to androgens through direct transcriptional regulation by the androgen receptor (AR)." (PMID 33310900, 2020). "Because it is located on the surface of prostate cells, we found that TMPRSS2 could be a potential marker for prostate cancer diagnosis." (PMID 33193689, 2020). "In lung and prostate cancer cells, TMPRSS2 expression is androgen dependent." (PMID 33117953, 2020). "In aggressive versions of prostate cancer, TMPRSS2 undergoes autocatalytic proteolysis at Arg255‐Ile256, where the two chains may remain in combination due to interchain disulphide bridges or the catalytic moiety may be secreted." (PMID 32358833, 2020). "Additionally, it has been reported that epigenetic events affected by genetic variation differentially regulate miRs in African American prostate cancer patients and are drivers of TMPRSS2:ERG-negative tumors." (PMID 33243086, 2020). "However, the ERG gene is consequently controlled by androgen receptor signaling and expressed highly in prostate cancers harboring the TMPRSS2–ERG fusion." (PMID 32992681, 2020). "TMPRSS2:ERG fusions occur in about 50% of prostate cancers, preferably in younger patients." (PMID 33339518, 2020). "Evidence also suggests that men with TMPRSS2:ERG positive tumors may have longer prostate cancer survival after androgen-deprivation therapy (ADT) and this is further discussed in the section of AR gene polymorphisms." (PMID 33243086, 2020).
prostate carcinoma (continued). "In prostate cancers, 40-80% of tumors harbor a gene fusion between the androgen receptor (AR)-responsive transmembrane protease serine 2 (TMPRSS2) gene and E26 transformation-specific (ETS) family transcription factor, most often the oncogene ETS-related gene (ERG)." (PMID 33135109, 2020). "Taken together, the findings that SARS-CoV-2 utilizes ACE2 and TMPRSS2 presupposes that SARS-CoV-2 could be an oncogenic virus for prostate cancer." (PMID 32974166, 2020). "TMPRSS2 was first identified to be highly expressed in prostate cancer." (PMID 32992681, 2020). "Several studies propose that TMPRSS2 is a prostate cancer marker, as fused with the ERG gene." (PMID 32970391, 2020). "TMPRSS2–ERG fusion is the most common oncogenic rearrangement in prostate cancer." (PMID 33243086, 2020). "Given these knowledge gaps, the goals of the current study were to determine which cells of the upper airway tract express ACE2 and TMPRSS2 and test whether their expressions could be therapeutically targeted by AR inhibitors used in prostate cancer treatment." (PMID 33310900, 2020). "Camostat is a pseudo irreversible inhibitor of different serine protease, including TMPRSS2, being characterized by aromatic guanidine as P1 mimetic recognition elements, less polar than Arg, and it is used in Japan for prostate cancer and other applications, such as pancreatitis and liver fibrosis." (PMID 32784899, 2020). "Prostate cancer ranks among the most frequent tumors and is a topic of particular interest during the pandemic as TMPRSS2 (and other serine proteases), which facilitate the entry, replication and budding of the virion from a cell can be inhibited using androgen deprivation therapy (ADT)." (PMID 32412310, 2020). "Similarly, TMPRSS2 mRNA expression is upregulated in androgen-activated prostate cancer cells; elevated TMPRSS2 mRNA expression is suggested to be facilitated by the androgen receptor." (PMID 32764454, 2020). "Through a HTS on FDA approved drugs and other commercial libraries (around 70 K cmpds) against TMPRSS2 in order to find new potential anti-metastatic agents for prostate cancer, bromhexine hydrochloride and other four hits were identified as inhibitors of the enzyme at a concentration below 5 μM." (PMID 32784899, 2020). "Though it is present in about 50% of prostate cancer, TMPRSS2-ERG fusion has not been consistently associated with clinical outcomes, while the loss of PTEN tumor suppressor gene was found to be of clinical prognostic value." (PMID 32957584, 2020). "Based on these findings, it can be hypothesized that TMPRSS2-ERG fusion positive prostate cancer patients are less vulnerable to SARS-CoV-2 infection." (PMID 33243086, 2020). "Furthermore, both in-vitro and in-vivo studies demonstrate treatment by androgen enhanced TMPRSS2 zymogen activation, thus implicating the role of TMPRSS2 in the onset and progression of prostate cancer in an androgen-dependent manner." (PMID 32764454, 2020). "Additionally, we revealed such genes for the TMPRSS2-ERG prostate cancer molecular subtype (B4GALNT4, ASRGL1, MYBPC1, RGS11, SLC6A14, GALNT13, and ST6GALNAC1)." (PMID 31447885, 2019). "Indeed, one of these studies even identified differences in the evolution of TMPRSS2-ERG+ vs. TMPRSS2-ERG− prostate cancers, based on whole genome sequencing of 112 primary and metastatic prostate tumours." (PMID 31275657, 2019). "To investigate the relationship between the germline variants involved in regulating TMPRSS2 expression levels and the TMPRSS2:ERG fusion oncogene, we applied our model of TMPRSS2 expression to the germline genotypes of TCGA prostate cancer cases to impute TMPRSS2 gene expression." (PMID 31308362, 2019). "Furthermore, the closest reported breakpoints in ERG fusions to the ERG breakpoints identified in our case (chr21:40033588) are seen in rare variants of TMPRSS2-ERG (only 1.17% of the characterized and reported ERG fusions in prostate cancer (COSF123))." (PMID 31906059, 2019).
prostate carcinoma (continued). "Thus, loss of ERF activity by rare genomic loss-of-function mutations or by competition with the TMPRSS2-ERG oncogenic product leads to activation of the androgen receptor pathway and prostate cancer." (PMID 31366128, 2019). "In addition, inhibit transcription of key androgen receptor regulated genes, such as KLK3 (PSA) and TMPRSS2 and induce apoptosis in both androgen-sensitive and castration-resistant prostate cancer cells." (PMID 31089377, 2019). "Prostate cancers with a positive TMPRSS2-ERG fusion show increased WNT signaling." (PMID 31434336, 2019). "Finally, it was provided evidence that TMPRSS2-ERG activates NOTCH signaling, thus inducing a druggable dependency on NOTCH signaling in TMPRSS2-ERG-positive prostate cancers." (PMID 31366128, 2019). "Our data support the development of the TMPRSS2-ERG fusion gene as a noninvasive tumor marker for therapy assessment, risk stratification, and relapse detection to improve personalized therapy strategies for patients with prostate cancer." (PMID 31915468, 2019). "Notably, in all TMPRSS2::ERG fusions present in prostate cancer, we identified more than one fusion splicing isoform." (PMID 31491926, 2019). "Therefore, we compared ERG-bound gene targets in HUVEC with those from human prostate epithelial cancer cell line (VCaP) prostate cancer cells carrying the TMPRSS-2:ERG gene fusion." (PMID 30892142, 2019). "It is important to note that prostate cancer exhibiting PTEN loss concomitantly displays TMPRSS2-ERG fusion; in contrast, not all of the TMPSS2-ERG fusion-positive tumors show PTEN deletion." (PMID 31366128, 2019). "Indeed, TMPRSS2:ERG fusion is frequently present in prostate cancer and known to activate the Wnt pathway through overproduction of the ERG protein, fully in line with our findings." (PMID 30733525, 2019). "Numerous fusion genes have been established as cancer drivers including BCR-ABL1 fusion in chronic myelogenous leukemia, TMPRSS2-ERG fusion in prostate cancer, EML4-ALK and CD74-NRG1 fusions in non-small cell lung cancer, and FGFR3-TACC3 in glioblastoma and bladder cancer." (PMID 31610622, 2019). "Comparison between human umbilical vein endothelial cell and prostate cancer TMPRSS2 (transmembrane protease, serine-2):ERG fusion-positive human prostate epithelial cancer cell line (VCaP) cells revealed distinctive lineage-specific transcriptome and super-enhancer profiles." (PMID 30892142, 2019). "In prostate cancer, recurrent fusions involving promoter regions of an androgen regulated gene, transmembrane protease serine 2 gene (TMPRSS2) fused to coding sequences of erythroblastosis virus E26 gene (ETS) family members have been identified in more than 50% of prostate cancer cases." (PMID 31106278, 2019). "Recent studies showed that TMPRSS2-ERG is a potential predictive biomarker for prostate cancer." (PMID 30459527, 2018). "In prostate cancer, the 5′-untranslated region of the TMPRSS2 gene is often translocated to the v-ets avian erythroblastosis virus E26 oncogene homolog (ERG) and ETS variant 1 (ETV1) gene, a member of the ETS gene family that is involved in a wide variety of functions, including cell proliferation." (PMID 29707137, 2018). "Although the prognostic implications of ETS rearrangements remain unclear, recent evidence suggests that TMPRSS2-ERG fusions are associated with young patients and low-grade prostatic cancer." (PMID 29581876, 2018). "VCaP cells are derived from a metastatic lesion to a lumbar vertebrae of a Caucasian male with hormone refractory prostate cancer; VCaP is a TMPRSS2-ERG fusion-positive prostate cancer cell line, expressing high levels of the androgen receptor splice variant AR-V7." (PMID 30296942, 2018).